XPO5 (exportin 5)
Diseases named in the same sentence as XPO5 in open-access papers (continued):
Sharing a sentence is not in itself a finding about the gene and the disease.
pneumonia (continued). "Moreover, genetic or pharmacological rescue of Dicer, XPO5, SRSF3, and hnRNPA3 expression relieves the N protein-induced DNA damage, proteotoxic stress, and pneumonia." (PMID 39138195, 2024). "Furthermore, Dicer, XPO5, SRSF3, and hnRNPA3 knockdown exaggerated the N protein-induced DNA damage, apoptosis, cytosolic DNA accumulation, upregulation of IFNβ, IL-6, and NKG2D ligands, and pneumonia." (PMID 39138195, 2024). "Here, we show that SARS-CoV-2 N protein induces the autophagic degradation of two RNAi components (Dicer and XPO5) and two splicing factors (SRSF3 and hnRNPA3), thereby inhibiting miRNA biogenesis and RNA splicing and triggering DNA damage, proteotoxic stress, and pneumonia." (PMID 39138195, 2024). "Although the expression levels of Dicer, XPO5, SRSF3, and hnRNPA3 were lower in the tissues of old mice than in those of young mice, PJ34 rescued the N-induced downregulation of Dicer, XPO5, SRSF3, and hnRNPA3 and ameliorated N protein-induced pneumonia not only in young mice but also in old mice." (PMID 39138195, 2024). "Furthermore, SARS-CoV-2 infection also led to the downregulation of Dicer, XPO5, SRSF3, and hnRNPA3 in mouse lung tissues, and overexpression of Dicer, XPO5, SRSF3, and hnRNPA3 in mouse lung tissues partially alleviated SARS-CoV-2-induced pneumonia." (PMID 39138195, 2024).
pneumonitis (1 paper, 2016). An inflammatory process affecting the lung parenchyma. "We observed that DGCR8 (p value: 0.010) and GEMIN4 (p value: 0.039) were significantly associated with pneumonitis, while XPO5 reached borderline significance (P = 0.087)." (PMID 26991123, 2016).
poisoning (1 paper, 2016). A condition or physical state produced by the ingestion, injection, inhalation of or exposure to a deleterious agent. "One SNP in XPO5 extron (rs2257082) was significantly associated with lead-poisoning (p = 0.022, odds rate (OR) = 1.63, 95% confidence interval (CI) = 1.07–2.47 in the C allele compared to the T allele)." (PMID 28042866, 2016).
Premature ovarian insufficiency (1 paper, 2014). Amenorrhea due to loss of ovarian function before the age of 40. "Our previous study revealed that the XPO5 rs2257082 allele was more frequently observed in premature ovarian insufficiency (POI) patients than in control subjects." (PMID 24769857, 2014).
prostate tumour (1 paper, 2013). "Thus it is possible that the lower levels of exportin-5 in metastatic prostate tumour cells lead to decreases in the mature miR-105 levels that we would have quantified using the Taqman microRNA assay system." (PMID 23950948, 2013).
renal cell carcinoma (1 paper, 2015). "In particular, XPO5 rs11077 was linked with increased risk of renal cell carcinoma in a recessive model." (PMID 26147304, 2015). "In addition, associations between polymorphisms in the XPO5 and AGO1 genes and renal cell carcinoma risk have been reported." (PMID 26147304, 2015).
squamous cell carcinoma (1 paper, 2011). A carcinoma arising from squamous epithelial cells. "Our findings indicate that SNPs in KRT81 and XPO5 could prove to be useful biomarkers for individualizing therapy in NSCLC patients and that KRT81 may be a novel immunohistochemical marker of squamous cell carcinoma, providing a new diagnostic tool to be used in therapeutic decision-making." (PMID 21799879, 2011).
type 2 diabetes mellitus (1 paper, 2019). A type of diabetes mellitus that is characterized by insulin resistance or desensitization and increased blood glucose levels. "Our study may provide a new clue of epidemiology about the importance of miRNA processing genes (RAN, XPO5, DICER1, and TARBP2) in type 2 diabetes mellitus and diabetic vascular complications." (PMID 31354628, 2019). "The effects of RAN, XPO5, DICER1, and TARBP2 SNPs on diabetes progression were further analyzed." (PMID 31354628, 2019).
cancer (41 papers, 2012 to 2025). A tumor composed of atypical neoplastic, often pleomorphic cells that invade other tissues. "While some XPO5 SNPs appear to confer risk in certain cancers, these associations seem to be SNP-specific and highly dependent on population characteristics." (PMID 41516223, 2025). "XPO5 mutations subsequently disrupt its role as a tumor suppressor gene and modulator for cancer through attenuated production of miRNAs that, in turn, promote growth regulatory gene TGGBR2 as well as proapoptotic gene BAX." (PMID 37373948, 2023). "Downregulation of miRNA processing genes (Dicer and several other proteins including Drosha, TARBP2, DGCR8 and XPO5) is an important cause for reduced levels of mature miRNAs in some cancer cells." (PMID 33917769, 2021). "We also excluded the frequent occurrence of specific indel hotspots in TRBP and XPO5 previously reported at high frequencies in cancers associated with MSI." (PMID 33406242, 2021). "In the XPO5 gene rs11077 SNP, the minor C allele significantly increased the risk of cancer (Log OR = 0.120, 95% CrI = 0.013, 0.241)." (PMID 32127945, 2020). "In particular, a number of studies have reported that XPO5 polymorphisms at the rs11077 locus affect disease development and patient survival in various cancers." (PMID 31374978, 2019). "Because aberrant expression of XPO5 increases the risk of cancer, it is a potential target for drug intervention." (PMID 24904827, 2014). "Exportin-5 mediates pre-miRNA nuclear transport into the cytoplasm, and some cancers possess loss-of-function mutations in this gene, which inhibits mature miRNA production." (PMID 23950948, 2013). "The XPO5*rs34324334 variant is thought to be in a highly conserved exportin-1/importin-b-like region and may affect the development of carcinomas." (PMID 37373948, 2023). "Our results suggest that XPO5 rs11077 may be a possible functional susceptibility locus for cancer risk." (PMID 32127945, 2020). "In addition, an increasing number of studies have focused on the correlations of XPO5 polymorphisms with cancer risk." (PMID 32127945, 2020). "In addition, mutations in XPO5 have been implicated in the development and progression of certain cancers." (PMID 31374978, 2019). "MiRNA dysregulations in human cancer are mainly due to genomic changes including amplification, mutation, deletion, and disturbance of miRNA biogenesis enzymes, namely, Drosha, exportin 5, Dicer, and argonaute 2 (ARO2), and effects of these changes show cell/organ specificity." (PMID 30596096, 2018). "Previous research has shown that XPO5 polymorphisms may vary across cancer types and populations." (PMID 41516223, 2025). "In the XPO5 gene rs11077 SNP, the minor C allele significantly increased the risk of cancer (Log OR = 0.120, 95% CrI = 0.013, 0.241), and a strong association between rs11077 SNP and cancer risk was also found in the dominant model (CC + AC vs. AA: Log OR = 0.132, 95% CrI = 0.009, 0.275)." (PMID 32127945, 2020). "As XPO5 is a key factor for the transportation of miRNA from the nucleolus, it has been postulated as a rate-limiting step in the development of miRNAs, so its impairment could lead to pre-miRNA trapping in the nucleolus, influencing the risk of cancer 60-61." (PMID 32127945, 2020). "For instance, in CRC cells, inhibition of XPO5 expression results in reduced cell proliferation and invasiveness, and induces G1-S phase cell cycle arrest, indicating that XPO5 plays a pivotal role in maintaining cancer cell growth and metastatic potential." (PMID 40657248, 2025). "Both increased and decreased expression levels of XPO5 have been observed across different cancer types." (PMID 41516223, 2025). "The XPO5*rs34324334 and RAN*rs14035 variants approached Hardy–Weinberg equilibrium among cancer-free controls (p-value > 0.05)." (PMID 37373948, 2023). "For the XPO5*rs34324334 variant, the most prevalent genotype (A/A genotype) in HCC patients was 43%, compared to 3.2% in cancer-free controls." (PMID 37373948, 2023).
cancer (continued). "MAGEC3 also upregulates a stress-related gene, WRNIP1, a DNA replication gene, MCM7, and cancer-related genes, XPO5 and ZSCAN16." (PMID 35158998, 2022). "In the present study, a total of five SNPs in XPO5 and RAN genes were comprehensively reviewed and analyzed to estimate their associations with the risk of overall cancer by Bayesian hierarchical meta-analysis." (PMID 32127945, 2020). "Several studies have inspected the association between XPO5 or RAN polymorphisms and the risk of various cancers, but the findings remain controversial." (PMID 32127945, 2020). "To substantiate the associations between the identified SNPs (XPO5 rs11077 and RAN rs3803012 SNPs) and cancer risk, we performed the eQTL analysis to assess the associations between SNPs and corresponding mRNA expression levels." (PMID 32127945, 2020). "On the basis of the Bayesian hierarchical meta-analysis, XPO5 rs11077 and RAN rs3803012 SNPs were significantly associated with the risk of cancer." (PMID 32127945, 2020). "Thirdly, studies of XPO5 and RAN SNPs in the cancer predisposition field continue to emerge, which resulted in limited number of the relevant investigations." (PMID 32127945, 2020). "Since the Bayesian hierarchical meta-analysis is much more sensitive and confers more precise estimation compared with classical meta-analysis, it is powerful suggested that rs11077 SNP of XPO5 and rs3803012 SNP of RAN are associated with cancer risk." (PMID 32127945, 2020). "A Bayesian hierarchical meta-analysis was carried out to review and analyze the effect of XPO5 and RAN polymorphisms on cancer risk." (PMID 32127945, 2020). "Formerly, several studies have been conducted to assess the association between XPO5 and RAN SNPs and cancer susceptibility in diverse populations." (PMID 32127945, 2020). "By cancer tissue microarrays (TMAs) and the cancer genome atlas (TCGA) RNA seq-data, it was shown that increased level of XPO5 promotes and sustain tumor including prostate cancer, breast cancer, ovarian cancer, and bladder cancer." (PMID 33330058, 2020). "In this review, we briefly describe the role of XPO5 in miRNA biogenesis and discuss its dysregulation in cancer." (PMID 29723684, 2018). "Previous studies have shown that microRNA machinery genes—such as DICER, DROSHA, XPO5, and RAN—are associated with cancer development." (PMID 27611467, 2016). "In this study, a meta-analysis was conducted to evaluate the association between SNPs in five genes (DROSHA, DGCR8, XPO5, RAN, and DICER1) involved in the canonical microRNA biogenesis pathway and human cancer risk." (PMID 27957388, 2016). "Previous studies have shown that several types of cancer are associated with alterations to miRNA machinery genes, such as DROSHA, DICER1, XPO5, and AGO2." (PMID 26147304, 2015). "In XPO5-mutant cancer cells, XPO5 transfection increases expression of the miR-200 family, let-7a and miR-26a (recognized tumor-suppressors), indicating that XPO5 has tumor-suppressive features." (PMID 26308063, 2015). "The expression levels of Drosha, DGCR8, Dicer, XPO5, AGO2, and TRBP have all been associated with several cancers." (PMID 24904827, 2014). "A recent study has shown that the XPO5 genetic defect traps pre-miRNAs in the nucleus of cancer cells, reduces miRNA processing, and diminishes miRNA-target inhibition." (PMID 22559327, 2012). "An increasing number of cancer studies have demonstrated that XPO5 possesses oncogenic properties." (PMID 40657248, 2025). "The exportin 5 (XPO5)/RAN‐GTP complex is essential for the nuclear export of precursor miRNAs (pre‐miRNAs), and alterations in the expression or function of its components have been linked to cancer risk." (PMID 41409896, 2025). "Importantly, many cancer-related changes in XPO5 expression appear to arise from somatic mechanisms, such as chromosomal amplification, epigenetic regulation, or transcriptional deregulation, rather than inherited germline variants." (PMID 41516223, 2025).
cancer (continued). "For example, genetic aberrations of cancer-associated genes belonging to the miRNA processing protein complex, such as TARBP2, DICER1, and XPO5, are of crucial importance in the cellular transformation pathways and contribute to an overall miRNA dysregulation in cancer." (PMID 38003902, 2023). "Additionally, we performed various bioinformatic analyses regarding the XPO5 and RAN genes to focus light on the importance of these potential variants in the progression of carcinomas." (PMID 37373948, 2023). "This fusion caught our attention as XPO5 is identified as an oncoprotein in several human cancers." (PMID 34944959, 2021). "XPO5/RAN-GTP complex mediates the nuclear transport of pre-miRNAs in the miRNA processing system, its altered expression is indicated to be correlated with cancer risk." (PMID 32127945, 2020). "In view of all this, Bayesian hierarchical meta-analysis suggests a potential role of the miRNA biogenesis genes XPO5 (rs11077 A/C) and RAN (rs3803012 A/G) SNPs in cancer risk, supplying novel clues to identifying new biomarkers with cancer-forewarning function." (PMID 32127945, 2020). "Therefore, in the present study, we carried out a Bayesian hierarchical meta-analysis including newly published articles to find a vivid and precise association between SNPs in XPO5 and RAN genes with cancer risk based on all available eligible studies." (PMID 32127945, 2020). "In addition, we compared mRNA expression levels of XPO5 in 154 paired cancer tissue samples with normal adjacent tissue samples from two TCGA projects (58 paired samples in TCGA-LIHC and 96 paired samples in TCGA-BRCA)." (PMID 32127945, 2020). "Conflicting roles for XPO5 have been found in different kinds of human cancers." (PMID 31371628, 2019). "Abnormal expression of XPO5 protein has been found in human cancers." (PMID 29723684, 2018). "Analysis of associations between SNPs from DROSHA, DGCR8, XPO5, RAN, and DICER1 and cancer risk." (PMID 27957388, 2016). "Additionally, the expression of proteins involved in miRNA biosynthesis, such as Drosha, Dicer, and Exportin-5, were analyzed and found to be significantly downregulated in human PC tissues as compared to the cancer-adjacent normal tissues." (PMID 26516699, 2015). "This could be attributed to the fact that some cancers have lower levels of functional exportin-5, an important miR biogenesis protein." (PMID 23950948, 2013). "Importantly, the restoration of XPO5 functions reverses the impaired export of pre-miRNAs and has tumor-suppressor features in a subset of cancers with microsatellite instability (MSI+)." (PMID 22559327, 2012). "Importantly, XPO5 expression is frequently dysregulated in cancer and may function either as an oncogene or tumor-suppressor, depending on the cellular context and cancer type." (PMID 41154621, 2025). "Despite the well established role of XPO5 in miRNA biogenesis and its documented dysregulation across multiple cancer types, the lack of association observed for rs11544382 in the present study suggests that not all XPO5 alterations contribute equally to carcinogenesis." (PMID 41516223, 2025). "Moreover, whether XPO5 functions as a tumor suppressor or oncoprotein in certain cancers should be investigated in animal model." (PMID 29723684, 2018). "Therefore, XPO5 could act as an oncoprotein and may be a potential therapeutic target in certain cancers." (PMID 29723684, 2018). "Interestingly, expression of wild-type XPO5 in these cells reverses the impaired export of pre-miRNAs and inhibits cancer cell growth, suggesting that XPO5 may function as a tumor suppressor in CRCs." (PMID 29723684, 2018). "Using two-box analysis of The Cancer Genome Atlas (TCGA) and Genotype-Tissue Expression (GTEx) databases, we compared the expression levels of XPO, including XPO1, CSE1L, XPOT, XPO5, and XPO6, in each tumor and normal tissue." (PMID 39882192, 2025).
cancer (continued). "We analyzed the mRNA expression levels of miRNA machinery components (DROSHA, DGCR8, XPO5, RAN, DICER, TARBP2, and AGO2) utilizing mRNA-Seq data from The Cancer Genome Atlas (TCGA) and The Genotype-Tissue Expression (GTEx) projects." (PMID 39404265, 2024). "Thus, the genetic variations of the XPO5 gene could imply various epigenetic alterations and posttranscriptional modifications that altered the expression patterns of the miRNAs, leading to the progression of different cancer diseases." (PMID 37373948, 2023). "Therefore, there may be some risks in targeting XPO5 for cancer treatment." (PMID 32754282, 2020). "Significantly altered functions, pathways, and gene networks revealed alterations in several key genes and cancer-related pathways that may have importance for NSCLC transformation, including FAM83A, ZNF696, UBE2C, RECK, TIMM50, GEMIN7, and XPO5." (PMID 35309509, 2022). "XPO5 represses HCC by potentiating the biogenesis of microRNAs, a class of small noncoding RNAs that regulate gene expression by repressing protein translation and generally inhibit cancer development." (PMID 33024085, 2020). "The microRNA (miRNA) expression levels are globally suppressed in human cancer compared to those in normal tissues, which are mostly contributed to genetic and epigenetic alterations in miRNA-processing machinery components such as DROSHA, DGCR8, XPO5, TARBP2, DICER, and AGO2 in human cancer." (PMID 30305728, 2019). "They find that a large number of MIR genes are transcribed and processed into pre-miRNAs, but not processed to mature miRNAs in cancer cells, indicating defects in the pre-miRNA nuclear export by XPO5 in human tumors." (PMID 29723684, 2018). "Evidence suggests that the genes XPO5 and RAN may contribute to the development of tumors, including HCC, and may be involved in the mechanism by which microRNAs (miRNAs) are synthesized in cancer." (PMID 37373948, 2023). "Moreover, gene interaction networks revealed several key genes and cancer-related pathways that may role for early NSCLC transformation and disease progression, including FAM83A, ZNF696, UBE2C, RECK, TIMM50, GEMIN7, and XPO5." (PMID 35309509, 2022). "Accumulating evidence indicates that some cancers and tumor cells are characterized by reductions in the levels of mature miRNAs compared to normal tissues or cells, which is due to reduced expression of Dicer and several other miRNA processing proteins (Drosha, TARBP2, DGCR8 and XPO5)." (PMID 33917769, 2021). "However, the results did not indicate a correlation between SNPs in XPO5 and RAN genes with cancer risk." (PMID 32127945, 2020).